MT2A (metallothionein 2A)
Diseases named in the same sentence as MT2A in open-access papers (continued):
Sharing a sentence is not in itself a finding about the gene and the disease.
cancer (continued). "In addition, there is an interactive relationship among EGF, growth factor, metallothionein 2A, and MMPs in malignant tumors." (PMID 38374934, 2024). "In some types of cancer, up-regulation of MT2A seems to play an adverse role in treatment." (PMID 34663301, 2021). "In addition, the survival analysis emphasized the prognostic significance of TRAFD1, SOD2, RIPK2, RBCK1, and MT2A as cancer-promoting factors in ccRCC and pRCC." (PMID 34795663, 2021). "Multiple studies have shown that MT2A expression is vital for the development of cancer." (PMID 34220318, 2021). "Moreover, high expression of MT2A in the cancer tissue correlated with poor prognosis of ESCC patients." (PMID 34572779, 2021). "Furthermore, the high expression of MT2A in the cancer stroma and cancer nest also correlated with poor prognosis of ESCC patients." (PMID 34572779, 2021). "The Kaplan–Meier analysis indicated that patients with a high expression of MT2A in the cancer stroma had significantly shorter OS (p = 0.046) and tended to have a shorter DFS (p = 0.066), while patients with a high expression of MT2A in the cancer nest had a significantly shorter CSS (p = 0.015)." (PMID 34572779, 2021). "Regardless of different types of cancers discussed in the literature, the findings are in line with other research suggesting potential role of MT2A SNP in determining the risk of neoplastic process." (PMID 26036762, 2015). "In addition, as clearly shown in the volcano plot, the presence of dysregulated genes required in copper homeostasis (MT1X, MT2A) might reflect the cancer cell’s response to AgNPs." (PMID 40076651, 2025). "Hence, we report that MT2A in CAFs and cancer cells contributes to ESCC progression." (PMID 34572779, 2021). "Additionally, ESCC patients with high MT2A expression in the cancer nest had a poor prognosis." (PMID 34572779, 2021). "We hypothesised that this repression of MT2A was involved in the 1,25D3-specific anti-proliferative function in LNCaP cells because recent reports suggested that the elevated expression of MTs was correlated with many types of cancer and their lethality." (PMID 29899561, 2018). "In addition, the negative association of EZH2 and MT1/MT2A genes in cancer cell lines and tissues was found in public gene expression database." (PMID 26973856, 2016). "In addition, negative association of EZH2 and MT1/MT2A expression is found in cancers including HCC." (PMID 26973856, 2016). "The drug sensitivities of MT2A, SLC7A5, and NOTCH1 were predicted in this study using the pan-cancer database of oncoPredict." (PMID 40133832, 2025). "Next, the correlation between MT2A, MT1E, MT1X expression and CD8+ T cells and other immune cells in various malignant tumors was analyzed by bioinformatics database." (PMID 36466860, 2022). "MT2A and SLC7A5 may be oxaliplatin-resistant genes unique to GC and thus were not significantly correlated with drug sensitivity in the pan-cancer database." (PMID 40133832, 2025). "Given that both MT2A and PKM2 are hypoxia-inducible genes and undergo mitochondrial translocation in response to hypoxia, we speculated that the expression levels of MT2A and PKM2 may exhibit a strong correlation in cancer." (PMID 41211480, 2025). "However, to the best of our knowledge, this is the first report on the role of MT2A in the ESCC microenvironment, including cancer cells and CAFs." (PMID 34572779, 2021). "Additionally, we found that nearly half of these 21 edges involved a protein of the Metallothionein family (i.e. MT1H, MT2A, MT1HL1, MT1X and MT1G), involved in the regulation of transcription factors and in cancers." (PMID 34197603, 2021).
cancer (continued). "MT2A and TRIM31 which were engaged in IFN-γ signaling, CDC6, SGK1 and PTP4A1 genes, presented a homogeneous expression pattern in both test and Validation datasets, although our results were contradictory to other studies in different cancers." (PMID 34249670, 2021). "MT2A immunoreactivities of spindle cells in the cancer stroma (representative of CAFs) and cancer cells in the cancer nest (representative of ESCC cells) were examined, and the patients were divided into two groups: high expression and low expression of MT2A." (PMID 34572779, 2021). "None of the 5 tested polymorphisms showed a correlation with cancer risk in studied groups, although for MMP-2, MMP-7 and MT2A non-significant differences in genotypes frequencies among cases and controls were observed." (PMID 32765800, 2020). "In contrast the expression of MT1X, MT2A, IL10RA, KIT was lower in cancer tissues as compared to normal tissues." (PMID 33240582, 2020).
infection (9 papers, 2010 to 2025). The state of being infected such as from the introduction of a foreign agent such as serum, vaccine, antigenic substance or organism. "MHBs levels after infection with MT2A were consistently below 25 ng/mL, just two-fold above the limit of detection (12 ng/mL)." (PMID 32517032, 2020). "For example, for ELVs harvested 24 hours post-infection, Metallothionein 2A is represented at 47.49-fold greater concentration in Toxo ELVs than SS ELVs, while whole cell expression of the same gene is only 0.89-fold." (PMID 24363837, 2013). "Furthermore, 72 h after infection, the expression levels of the metallothioneins metallothionein 2A (MT2A) (3.03) and metallothionein 1A (MT1A) (2.58) increased the most, while the lowest FC index was found for the gene encoding the calcium-binding protein S100G (−2.64)." (PMID 35746747, 2022). "A larger overlap in DEGs was noted between the two time points in the infection group with 74 DEGs that enriched to processes involved in wound repair (HBEGF and MT2A) as well as immune responses to pathogens (CCL20, IL6, and SLAMF1)." (PMID 40576342, 2025). "To evaluate the function of MT2A in HL60 cells, we up-regulated its endogenous expression by infection of GV492-MT2A." (PMID 34220318, 2021).
neurodegenerative disease (3 papers, 2017 to 2023). A disorder of the central nervous system characterized by gradual and progressive loss of neural tissue and neurologic function. "We also noted that other genes like MT-CO2, MT2A, and ABCG1 are placed in specific nodes of our molecular networks, thus suggesting that they may play important role/s in ALS, as it has been already reported in other neurodegenerative diseases like AD." (PMID 30210287, 2018).
head and neck tumors (1 paper, 2015). "The results indicate that the presence of an SNP in the core promoter region at locus −5 A/G (rs28366003) in the MT2A gene contributes to a higher risk of malignant head and neck tumors." (PMID 26036762, 2015). "Moreover, this is also the first study to investigate the expression of MT2A isoforms in IP biopsy tissue and to document the relationship between MT2A SNPs and aggressive phenotype of this type of head and neck tumor." (PMID 26036762, 2015).
MT2A also shares sentences with these, for which no sentence is quoted: asthma (4 papers); colitis (3); Parkinson disease (3); Zinc deficiency (3); brain disorder (2); cardiac hypertrophy (2); Crohn disease (2); glioma (2); injury (2); liver cancer (2); liver fibrosis (2); lymph node metastasis (2); neuropathy (2); Stroke (2); adrenocortical cancer (1); amyotrophic lateral sclerosis (1); Arthritis (1); autism (1); autism spectrum disorder (1); brain injury (1); breast (1); breast tumor (1); cardiac failure (1); cataract (1); Cerebral ischemia (1); Down syndrome (1); endothelial dysfunction (1); Fuchs’ dystrophy (1); gastritis (1); glioblastoma (1).
A further 17 diseases each share a sentence with MT2A in 1 paper.